TNF (tumor necrosis factor)
Diseases named in the same sentence as TNF in open-access papers (continued):
Sharing a sentence is not in itself a finding about the gene and the disease.
COVID-19 (continued). "These migratory DCs express IL10 in health, but TNF and the common IL-12 and IL-23 subunit IL12B in COVID-19, suggesting altered capacity for T cell polarization." (PMID 33879890, 2021). "In addition, there were some data that even suggested that persons using anti-TNF agents may be at lower risk than non-users for developing severe COVID-19." (PMID 34755038, 2021). "In the COVID-19, Th1 cells were significantly higher than Th2 CD4+ T cells, which produced IL-4, IL-2, and TNF, main markers for Th2 response." (PMID 34571855, 2021). "In this study, we found that inflammatory biomarkers (IL-6 and TNFα) and GAC markers (Hyal and SDC1) were elevated in hospitalized COVID-19 patients compared with HC." (PMID 34792686, 2021). "In our study, the levels of seven cytokines in COVID-19 patients (IL-6, IP-10, IL-8, MIG, MIP-1β, IL-18, TNF-α) were different from those in healthy controls, while M-CSF, MCP-1, FLT-3, VEGF, IL-1RA, EGF, eotaxin and MCP-1 were not different." (PMID 34539644, 2021). "In the process of COVID-19, elevated plasma levels of IL-6, IFN-γ, IL-2, IL-7, IL-15, G-CSF, MCP1, MIP1α, and TNF were observed." (PMID 34945800, 2021). "The discovery downstream of this inflammatory cell death pathway mediated by TNF-α and IFN-γ resulted in the identification of multiple drug targets for COVID-19 and other infectious or inflammatory diseases involving cytokine storm." (PMID 34946543, 2021). "This study evaluated TNF, TNFRs, and ADAM17 at the protein, transcriptional, and gene levels in COVID-19 patients with different levels of disease severity." (PMID 34445140, 2021). "Subjects suffering from COVID-19 express a range of similar symptoms such as lymphopenia, hypercoagulability, and cytokine storm (elevation in IL-6, CRP, TNF, MCP1, IL-1β levels, and others)." (PMID 34680053, 2021). "Numerous studies have shown that hyperinflammation and cytokine storms, as well as increased levels of pro-inflammatory cytokines IL-6, -8, -2, -10, TNF-α, and IFN-α, correlate with the severity of COVID-19 and poor outcomes." (PMID 34603758, 2021). "Levels of IL-6, IL-10, IL-15, IFN-γ, TNF-α, CCL2, CCL3, CCL4, CCL26, CXCL9 and CXCL10 were significantly elevated both in COVID-19 critical clinical condition and in MAS patients as compared to healthy controls." (PMID 34226537, 2021). "The experimental use of DNase-1-coated melanin-like nanospheres on plasma of COVID-19 patients resulted in significant reduction of NETs and MPO activity, as well as the decrease of the cytokines IL-1b, IL-6, and TNFα, involved in the NETs pathological loop." (PMID 34445556, 2021). "According to the results of the KEGG pathway analysis, the TNF signaling pathway is the most significant pathway in which the core target AKT1, that is the core target of junction targets to XBJ injection and COVID-19, was involved." (PMID 34077310, 2021). "In the current study, we observed robust increases of proinflammatory cytokines/chemokines in sera and BALF, such as TNF-α, IL-1β, IL-6, KC, MCP-1, RANTES, and MIP-1α/β27,28 which correlate with those observed in severe COVID-19 and ARDS patients." (PMID 34952899, 2021). "In this article, we summarize reports on the plasma levels of cytokines IL-6, TNF-α and IL-28B and the biomarkers of cardiovascular disease, cTnT, NT-proBNP, PAPP-A and IMA, in a retrospective study of 84 patients with COVID-19." (PMID 34884175, 2021). "During the early stage of the pandemic, the upregulation of many cytokines, including interleukin (IL)-6, IL-1β, tumor necrosis factor α (TNF-α), and interferons, was observed in patients with COVID-19." (PMID 34001144, 2021). "IFN-γ was lower in the SEVERE COVID-19 group when compared to COVID-19 MILD, while pro-inflammatory cytokine levels (IL-6, TNF-α, and MCP-1) were higher." (PMID 34315957, 2021).
COVID-19 (continued). "Regarding the pathway enrichment analysis, the present study shows that the IL-17, IL-6, TNF-α, and IFN signals, complement system, and growth factor receptor signaling were major pathways by which GA targets COVID-19." (PMID 34177566, 2021). "In COVID-19 patients, the hyperproduction of proinflammatory cytokines, such as IL-1, IL-6, IL-12, IFN-γ, and TNF-α, helps determine the severity of the disease." (PMID 34635175, 2021). "Similar conclusions were drawn for patients with hidradenitis suppurativa treated with the anti-tumor necrosis factor (TNF) α adalimumab, who showed a low prevalence of COVID-19 (1%) in a high-epidemic area (Milan, Italy)." (PMID 33936084, 2021). "Inflammatory parameters (IL-6, IL-10, TNF-alpha, IFN-gamma, MCP-1) were increased in COVID-19 patients with severe illness." (PMID 35136584, 2021). "The overproduction of early response cytokines, such as tumor necrosis factor (TNF), interleukin-6 (IL-6) and interleukin-1β (IL-1β), has been described in patients severely affected by COVID-19." (PMID 33240326, 2020). "We also discovered there were higher levels and proportion of the elevation of LDH, IL-2R, IL-6, IL-8, IL-10 and TNF-α, furthermore, there were only higher levels of CRP and ferritin in the critically ill COVID-19 patients." (PMID 32788884, 2020). "According to a recent report analyzing 138 hospitalized patients with COVID-19 high plasma concentrations of cytokines and chemokines including IL-2, IL-7, IL-10, G-CSF, IP-10, MCP-1, MIP-1A, and TNF-α were observed in the COVID-19 severe cases." (PMID 33154753, 2020). "After univariate and multivariate logistic regression, the levels of hs-CRP, IL-6, and TNF-α were shown to be positively correlated with the incidence of myocardial injury, supporting the hypothesis that a high systemic inflammatory burden might contribute to myocardial injury in COVID-19 patients." (PMID 32733921, 2020). "The activated mechanistic networks in patients with severe COVID-19 highlighted the predicted relationship between IL1A, IL1B, and TNF, and their regulation in gene datasets based on Z scores." (PMID 33138195, 2020). "Pro-inflammatory cytokines and anti-inflammatory cytokines in serum, including IL-2R, IL-6, TNF-α, and IL-10, were significantly higher in most severe patients than in moderate patients, suggesting that cytokine storms may be related to the severity of COVID-19." (PMID 33232275, 2020). "As cytokine storms played a critical role in the deterioration of COVID-19, we also detected the Th1/Th2 cytokines including IL-2, IL-4, IL-6, IL-10, TNF-α, and IFN-γ in patients infected with COVID-19." (PMID 33061829, 2020). "In COVID-19 patients, the majority of the CD73-CD8+ T cells were capable of secreting granzyme B, perforin, tumor necrosis factor (TNF-α) or interferon-gamma (IFN-γ)." (PMID 32707842, 2020). "When we directly compared COVID-19 and influenza, NFKB1, NFKB2, and TNF were up-regulated in COVID-19, whereas STAT1, TLR4, and genes for immunoproteasome subunits were up-regulated in influenza." (PMID 32651212, 2020). "Moreover, given the recent evidence in different hospitals suggesting IL-6 and TNF-α inhibitor drugs as a possible therapy for COVID-19, we aimed to highlight that a dietary intervention could be useful to prevent the infection and/or to ameliorate the outcomes during therapy." (PMID 32354030, 2020). "Significantly up-regulated levels of cytokines and chemokines including IL1-β, IL1RA, IL10, IL9, IL8, IL7, basic FGF2, GCSF, GMCSF, IFNγ, IP10, MCP1, MIP1α, MIP1β, PDGFB, TNFα, and VEGFA in blood, have been confirmed in COVID-19 patients." (PMID 33041797, 2020). "Virus-specific T cells from severe COVID-19 patients also highlight a central memory phenotype with high levels of interferon (IFN)-γ, tumor necrosis factor (TNF)-α, and IL-2." (PMID 33344479, 2020).
COVID-19 (continued). "Using the functional network analyses of DEGs, DEmiRNAs and DElncRNAs, we found that the TNF, MAPK, and NF-κB signaling pathways are the most significantly changed pathways during recovery from COVID-19." (PMID 33361761, 2020). "In a study published in the Lancet, COVID-19 patients exhibit increased plasma levels of cytokines and chemokines, such as IFNγ, CXCL10, IL-1β, and TNFα." (PMID 32431755, 2020). "Severe cases of COVID-19 tend to have lower lymphocyte counts and higher plasma levels of LDH and TNF-α." (PMID 33147282, 2020). "Hospitalized patients with severe COVID-19 show high levels of IL-2, IL-7, IL-10, G-CSF, TNF, CXCL10, MCP1, and MIP1α in serum, suggesting that severe COVID-19 is dictated as a cytokine release syndrome (CRS), which is a disorder induced by cytokine storms." (PMID 33014208, 2020). "In conclusion, our findings suggest that both COVID-19 and AOSD have elevated level of ferritin and cytokines, including IL-1β, IL-6, IL-10, IL-18, and TNF-α, indicating systemic inflammation in the pathogenesis of COVID-19 and AOSD." (PMID 33552062, 2020). "Higher percentages of CD4+ T cells producing IFNγ, TNFα, IL-2, and IL-17A and CD8+ T cells producing IL-2 and IL-17A have been detected by flow cytometry in PBMCs from COVID-19 patients vs. healthy controls after in vitro stimulation." (PMID 33634100, 2020). "The expression of several cytokines identified in the current study (i.e., IL1B, IL-6, TNF, CCL2, CXCL9, and CXCL10) were also seen in bronchoalveolar lavage (BAL) cells from COVID-19 patients, providing further support to our observation." (PMID 32882823, 2020). "NF-κB controls the expression of many pro-inflammatory cytokines, including IL-1β, TNF-α, IL8, IL-6, all of which are induced in the cytokines storm syndrome and in COVID-19." (PMID 32708322, 2020). "The stimulation of PBMCs from COVID-19 patients with S protein peptides resulted in production of effector or Th1 cytokines (IFN-γ, TNF-α, and IL-2) and, to a lesser extent, Th2 (IL-5, IL-13, IL-9, and IL-10) and Th17 (IL-17A, IL-17F, and IL-22) cytokines." (PMID 32916812, 2020). "Early positive investigation results included a positive COVID-19 swab test, raised CRP, ferritin, D-dimer and TNF-alpha, characteristic of proinflammatory states." (PMID 32696735, 2020). "Increase in mortality in those with COVID-19 is due to acute respiratory distress syndrome (ARDS) due to unantagonized production of pro-inflammatory cytokines IL-6 and TNF-α." (PMID 33390994, 2020). "Endotoxin stimulates the production of interleukin 6 (IL-6), IL-1, IL-8, tumor necrosis factor alpha (TNF-α), and gamma interferon (IFN-γ), cytokines that are also found in COVID-19 patients." (PMID 32703911, 2020). "Indeed, defined circulating factors - CXCL8, IL-10, IL-15, IL-27, and TNF-α - positively correlate with older age, longer hospitalization, and a more severe form of the disease and may thus represent the leading signature in critical COVID-19 patients." (PMID 33159040, 2020). "There are higher levels of inflammatory factors, including IL-2, IL-4, IL-6, IL-10, TNF-α, and IFN-γ, found in COVID-19 patients than in healthy people." (PMID 32985562, 2020). "A prior study found that the number of T cells was drastically decreased, while the level of TNF, IL6, and IL10 were significantly increased in severe COVID-19 patients compared to healthy control." (PMID 33362771, 2020). "We therefore examined the concentrations of serum cytokines, including TNF-α, IFN-γ, IL-2, IL-4, IL-6, and IL-10, from these COVID-19 patients to explore the influence of cytokine signaling." (PMID 32425950, 2020). "In COVID-19, a significant elevation of cytokines (interferon [IFN]-γ, tumor necrosis factor [TNF]-α, interleukin [IL]-6, IL-10, IL-2, IL-1, and others) and lymphocytopenia are found." (PMID 32510901, 2020). "Both TNF/IL-1β-responsive genes and IFN-I-responsive genes were enriched in severe COVID-19-specific up-regulated genes." (PMID 32651212, 2020).
COVID-19 (continued). "It is believed that a large number of COVID-19 patients will go on to develop pulmonary fibrosis, and that these changes are mediated by a number of cytokines including TGF- ß, IL-1, IL-6, and TNF-α." (PMID 33082935, 2020). "Inflammatory genes such as IL1B, TNF, and CXCL8 were also increased during aging and were further upregulated in COVID-19." (PMID 32780218, 2020). "We measured plasma concentrations of TNF, IL-1β, IL-6, IFN-β, IFN-γ, and IL-18 in a larger cohort of COVID-19 patients." (PMID 32651212, 2020). "COVID-19 patients had lower levels of most classical inflammatory cytokines (G-CSF, CCL20, IL-1β, IL-2, IL-6, IL-8, IL-15, TNF-α, TGF-β), but higher plasma concentrations of CXCL10, GM-CSF and CCL5, compared to non-COVID-19 patients." (PMID 33272291, 2020). "Just as in COVID-19, atherosclerosis involves a predominance of TH1 response, involving IFN-γ, TNF-α, and TNF-β, which amplify the inflammatory response." (PMID 34211530, 2020). "Since high plasma levels of TNF-α have been widely observed in our patients, it is worth investigating the effects and safety of TNF-α inhibitors in the treatment of COVID-19." (PMID 32733921, 2020). "Increased pro-inflammatory cytokines and neutrophils infiltration were present in severe COVID-19 patients, in our murine ARDS model, we noticed the increased pro-inflammatory cytokines IL-6, TNF-α, and IL-1α in BALF." (PMID 33584719, 2020). "A previous study demonstrated the changes in the levels of inflammatory cytokines, such as IL-2, IL-7, IL-10, and tumor necrosis factor (TNF)-α, in the serum of COVID-19 patients." (PMID 32484453, 2020). "In COVID-19, TACE-dependent TNF shedding favors the rapid breakdown of the endothelial-alveolar barrier, resulting in lung edema, immune cell infiltration, and ultimately, lung tissue damage." (PMID 33101215, 2020). "Independent of its antiviral effects, GQ20-PTO additionally suppressed IFNβ and IL-6 (but not TNFα) signaling and the formation of reactive oxygen species, processes known to contribute to hyperinflammation in severe COVID-19." (PMID 41851107, 2026). "This study specifically examined the spike-specific immune response following a third dose of mRNA COVID-19 vaccines by assessing Th1 cytokines (IFN-γ, IL-2, and TNF-α) and IP-10 production using an easy-to-use whole-blood assay in PwMS undergoing various DMTs." (PMID 41246331, 2025). "The marked impairment of SARS-CoV-2 neutralization activities among anti-TNF-treated IBD patients is a critical finding, as these could potentially lead to dismal protection from symptomatic SARS-CoV-2 infection and severe COVID-19." (PMID 40733650, 2025). "And two were associated with COVID-19 in men and not in women: MIP-1α (OR in men = 7.0), and TNF-α (OR = 0.2; both p ≤ 0.02); this was similarly observed above for seropositivity (section 3.1)." (PMID 40910046, 2025). "This study aimed to identify whether TNF and IFN-γ levels play a central role in regulating the activated state of immune cells in COVID-19 patients and explore potential links with TLR7 and TLR8 signaling." (PMID 39940907, 2025). "Our study confirms that TNF-α inhibitors and IL-17 inhibitors did not significantly impact COVID-19 severity (p = 0.882), aligning with global findings." (PMID 40142222, 2025). "Moreover, the study explores sex-specific differences in inflammatory markers (e.g., TNF-α and IL-8), and in SARS-CoV-2-specific T-cell response, contributing to the growing evidence of sex-related disparities in COVID-19 and long COVID outcomes." (PMID 41226453, 2025). "The cytokine profiles of COVID-19 and IPF show significant overlap, particularly in the elevation of profibrotic and proinflammatory mediators such as transforming growth factor-beta (TGF-β), interleukin-6 (IL-6), and tumor necrosis factor-alpha (TNF-α)." (PMID 40806851, 2025).
COVID-19 (continued). "We observed higher levels of bilirubin, D-dimer, C-reactive protein, urea, and plasmatic cytokines, such as IL-1β, IL-6, IL-8, IL-10, IL-17A, IL-23, TNF-α, and IFN-α in individuals with the critical form of acute COVID-19 compared to individuals with the severe and/or moderate WHO clinical forms." (PMID 39861879, 2025). "Although most of the components of cellular response and cytotoxicity that we examined were studied after COVID-19 vaccination in the general population (NRF2, TRAIL, LT-α, Fas), only some were studied in people with AIIRD (IL-2, TNF, perforin, granzymes, FasL)." (PMID 40226625, 2025). "In contrast, COVID-19 negative individuals showed lower-magnitude responses for TNF, IL-10, and IL-17A but exhibited multiple peaks in IL-2, IL-6, and IFN-γ production." (PMID 40406109, 2025). "These included IL-6, TNF-α, CCL5, and CXCL2 with expression levels significantly surpassing those observed in SARS-CoV-2 and HKU4 controls, which were positively related to severity in COVID-19 patients." (PMID 40774246, 2025). "Studies have shown that elevated serum levels of inflammatory cytokines such as IL-6 and TNF-α at the time of hospitalization are strong negative prognostic markers in COVID-19 patients." (PMID 40677723, 2025). "In parallel, the pandemic has underscored the role of a dysregulated immune response, known as cytokine release syndrome (CRS), characterized by the overproduction of inflammatory cytokines like TNF-α, IL-6, IL-1β, and IFN-γ, which serve as inflammatory biomarkers of COVID-19." (PMID 40649865, 2025). "Similarly, inflammatory cytokines including IL-6, tumor necrosis factor-alpha (TNF-α), and CRP were elevated in patients with COVID-19 at baseline compared with levels in healthy controls in both the RoW and US studies." (PMID 40461100, 2025). "A leading, indirect pathway is inflammation-driven tumor promotion, particularly through IL-6/JAK–STAT3, IL-1β/NLRP3, TNF-α/NF-κB, and ELR+ CXC chemokines (e.g., IL-8/CXCL8), which are all engaged during COVID-19 and have established roles in lung tumor biology." (PMID 41440526, 2025). "Severe SARS-CoV-2 infection induces aberrant innate immune activation with elevated IL-6, IL-1β, TNF-α, and other soluble mediators; this hyperinflammatory state is a potent nonspecific mechanism of multi-organ injury in severe COVID-19." (PMID 41462971, 2025). "Notably, convalescent serum showed significant decreases in sICAM-1, sVCAM-1, P-selectin, IL-1α, IL-1ra, IL-10, IL-27, TNF-α, TGF-α, and G-CSF compared to serum from severe COVID-19 patients." (PMID 41583455, 2025). "Escalating concentrations of recombinant spike can activate human lung macrophages, triggering the production of proinflammatory cytokines that mirror the “cytokine storm” signature observed in clinical COVID-19 cases (IL-2, IL-4, IL-6, IL-1β, IL-8, IFN-γ, TNF-α, and CXCL10)." (PMID 41012643, 2025). "Notably, the exacerbation in the late stages of COVID-19 has been found to correlate with specific biomarkers of CRS, including interleukin-1β (IL-1β) and tumor necrosis factor-α (TNF-α)." (PMID 41357188, 2025). "Together with decreased levels of TNF-α, granzyme B, and IFN-γ, cell markers such as NKG2A in NK cells may indicate a mechanism that both exhausts NK cells in COVID-19 patients and prevents their production." (PMID 40497938, 2025). "In contrast, the levels of TNF-α and IL-10 were not significantly different between the severe and non-severe COVID-19 groups." (PMID 39859379, 2025). "Our findings suggest that the TNF pathway may be explored as a potential therapeutic target to prevent PIMS complications in children and, presumably, in severe COVID-19 in adults." (PMID 39940694, 2025).